RTF1 (RTF1 homolog, Paf1/RNA polymerase II complex component)
Description:
Component of the PAF1 complex (PAF1C) which has multiple functions during transcription by RNA polymerase II and is implicated in regulation of development and maintenance of embryonic stem cell pluripotency. PAF1C associates with RNA polymerase II through interaction with POLR2A CTD non-phosphorylated and 'Ser-2'- and 'Ser-5'-phosphorylated forms and is involved in transcriptional elongation, acting both independently and synergistically with TCEA1 and in cooperation with the DSIF complex and HTATSF1. PAF1C is required for transcription of Hox and Wnt target genes. PAF1C is involved in hematopoiesis and stimulates transcriptional activity of KMT2A/MLL1; it promotes leukemogenesis through association with KMT2A/MLL1-rearranged oncoproteins, such as KMT2A/MLL1-MLLT3/AF9 and KMT2A/MLL1-MLLT1/ENL. PAF1C is involved in histone modifications such as ubiquitination of histone H2B and methylation on histone H3 'Lys-4' (H3K4me3). PAF1C recruits the RNF20/40 E3 ubiquitin-protein ligase complex and the E2 enzyme UBE2A or UBE2B to chromatin which mediate monoubiquitination of 'Lys-120' of histone H2B (H2BK120ub1); UB2A/B-mediated H2B ubiquitination is proposed to be coupled to transcription. PAF1C is involved in mRNA 3' end formation probably through association with cleavage and poly(A) factors. In case of infection by influenza A strain H3N2, PAF1C associates with viral NS1 protein, thereby regulating gene transcription. Binds single-stranded DNA. Required for maximal induction of heat-shock genes. Required for the trimethylation of histone H3 'Lys-4' (H3K4me3) on genes involved in stem cell pluripotency; this function is synergistic with CXXC1 indicative for an involvement of a SET1 complex (By similarity).
Synonyms: KIAA0252; GTL7
Tractability: PROTAC: ubiquitination databases record sites on it; its protein half-life has been measured.
Gene: Protein-coding gene on chromosome 15 (41,408,408 to 41,483,563, forward strand). Ensembl gene ENSG00000137815.
Subcellular location: Nucleus, nucleoplasm
Subcellular location (Human Protein Atlas): Nucleoplasm; Cytosol
Pathways (Reactome):
Gene expression (Transcription): Formation of RNA Pol II elongation complex; RNA Polymerase II Pre-transcription Events; RNA Polymerase II Transcription Elongation
Chromatin organization: CHD1 and CHD2 subfamily
Disease: Dengue virus activates/modulates innate and adaptive immune responses
Metabolism of proteins: E3 ubiquitin ligases ubiquitinate target proteins
Gene Ontology:
Molecular function: protein binding; RNA binding; single-stranded DNA binding; DNA binding
Biological process: stem cell population maintenance; transcription elongation by RNA polymerase II; endodermal cell fate commitment; negative regulation of transcription by RNA polymerase II; chromatin organization
Cellular component: Cdc73/Paf1 complex; nucleus; nucleoplasm; nucleolus
Genetic constraint (gnomAD): Loss-of-function variants: 9 observed, 70.44 expected, observed/expected ratio (o/e) 0.13, 90% interval 0.076 to 0.22. The upper end of that interval is the gene's LOEUF score, 0.22, which puts it in group 1 of 6, group 1 being the genes least tolerant of losing a copy. Missense variants: 408 observed, 759.55 expected, observed/expected ratio (o/e) 0.54, 90% interval 0.49 to 0.58. Synonymous variants: 279 observed, 275.92 expected, observed/expected ratio (o/e) 1.01, 90% interval 0.92 to 1.12.
Homologues: Orthologues: chimpanzee RTF1 (100% identical), macaque RTF1 (100% identical), rabbit RTF1 (99% identical), dog RTF1 (99% identical), pig RTF1 (99% identical), guinea pig RTF1 (98% identical), rat Rtf1 (98% identical), mouse Rtf1 (98% identical), tropical clawed frog rtf1 (83% identical), zebrafish rtf1 (80% identical), Drosophila melanogaster tplus3a (16% identical), Drosophila melanogaster tplus3b (16% identical), and 1 more.
Diseases named in the same sentence as RTF1 in open-access papers:
RTF1 is named in the same sentence as 19 diseases in open-access papers, as found by Europe PMC text mining. Sharing a sentence is not in itself a finding about the gene and the disease. The quoted sentences say what the papers report.
cerebral atherosclerosis (1 paper, 2021). Atherosclerosis of the cerebral vasculature. "Notably, CNOT3 protein has evidence for physical interactions in the BioGRID dataset with two proteins we previously found associated with cerebral atherosclerosis in human brain, HNRNPLL and RTF1." (PMID 34073619, 2021).
COVID-19 (1 paper, 2025). A disease caused by infection with severe acute respiratory syndrome coronavirus 2. "Within the dataset analyzed in this study, 4 out of 27 genes (14,8%) showed the 3′UTR shortening mechanism via APA (Δusage < −0.3), providing specific examples of potential escape from miRNA regulation in COVID-19 patients: CCNG2, PGS1, RTF1 and SPCS3." (PMID 41168347, 2025).
cryptococcosis (1 paper, 2025). An acute or chronic, localized or disseminated infection by Cryptococcus neoformans. "Next, we investigated whether Rtf1 HMD domain is involved in the production of major virulence factors in vitro and pathogenicity in murine models of cryptococcosis." (PMID 40353352, 2025).
dilated cardiomyopathy (1 paper, 2023). Cardiomyopathy which is characterized by dilation and contractile dysfunction of the left and right ventricles. "Taken together, these data suggest that loss of Rtf1 in the adult myocardium causes progressive left ventricular systolic dysfunction culminating in dilated cardiomyopathy and heart failure." (PMID 37233188, 2023). "Consistent with these phenotypic parallels, we also identified a significant enrichment in genes associated with dilated cardiomyopathy among those genes that were differentially expressed after 3 weeks of Rtf1 loss of function." (PMID 37233188, 2023). "Together, these results demonstrate that loss of Rtf1 activity in the adult mouse myocardium not only induces functional changes like those observed in human dilated cardiomyopathy, but also gene expression changes as well." (PMID 37233188, 2023). "Rtf1 knockout hearts eventually fail and exhibit structural and gene expression defects resembling dilated cardiomyopathy." (PMID 37233188, 2023). "Rtf1 knockout hearts are dilated and only very weakly contract, resembling human dilated cardiomyopathy." (PMID 37233188, 2023). "Interestingly, intercalated disc abnormalities and decreased N-cadherin protein have been associated with dilated cardiomyopathy in human patients, suggesting that Rtf1 knockout hearts also have cellular-level similarities to dilated cardiomyopathy." (PMID 37233188, 2023).
heart failure (1 paper, 2023). Inability of the heart to pump blood at an adequate rate to meet tissue metabolic requirements. "Together, these data demonstrate the Rtf1-deficiency-induced heart failure is characterized by disrupted myofibril organization, defective intercalated disc structure, and widespread fibrosis." (PMID 37233188, 2023). "While further studies would be required to identify the cell types upregulating cell division genes in the Rtf1 knockout left ventricle, we hypothesize these gene expression changes may be pathogenic and reflect fibrosis in the myocardium during heart failure." (PMID 37233188, 2023). "We sought to understand the gene expression changes resulting from loss of Rtf1 activity in the adult myocardium, including both early/primary and late/secondary transcriptional responses to Rtf1 deficiency that underly the dramatic heart failure phenotype we observed." (PMID 37233188, 2023). "To further examine the gene expression changes associated with Rtf1 knockout-induced heart failure, we tested the set of genes that was differentially expressed three weeks following the induction of Rtf1 knockout for enrichment of Human Phenotype and KEGG gene set ontologies." (PMID 37233188, 2023).
meningitis (1 paper, 2025). A disorder characterized by acute inflammation of the meninges of the brain and/or spinal cord. "Here, we show that Rtf1 is required for facilitating H2B monoubiquitination (H2Bub1), and regulates fungal morphogenesis and pathogenicity in the meningitis-causing fungal pathogen Cryptococcus neoformans." (PMID 40353352, 2025).
cancer (3 papers, 2016 to 2023). A tumor composed of atypical neoplastic, often pleomorphic cells that invade other tissues. "Indeed, our data and those obtained in cancer cells suggest that Rtf1 could integrate into Paf1C transiently, forming a distinct module with alternative functions and the potential to regulate distinct genes." (PMID 26765774, 2016). "Similarly, some progressors (CHMP4B, CSTF1, and LSM14B) and suppressors RBPs (ATP5F1A, GTF2E2, RTF1, ELAC2, LRRC47, and MRM3) have never been associated with COAD or READ, but present oncogenic properties in other cancer types." (PMID 37384253, 2023).
heart disease (1 paper, 2023). "Future investigation of the specific transcription regulatory mechanisms influenced by Rtf1 is likely to provide basic information about how cardiac genes are regulated and may lead to therapeutic advances for treating heart disease." (PMID 37233188, 2023).
immune diseases (1 paper, 2008). "We identify four nuclear proteins, HDAC5, TFC4, RTF1 and POLDIP3 polymerase as new autoantigens that could be used as markers in the diagnosis of subfamilies in immune diseases, although we cannot determine the role of these proteins in the aetiopathogenic process." (PMID 18625050, 2008).
infection (1 paper, 2011). The state of being infected such as from the introduction of a foreign agent such as serum, vaccine, antigenic substance or organism. "A striking observation is that enhancement of infection results after independent knockdown of 3 components of the PAF1 complex (PAF1c), PAF1, CTR9 and RTF1 (A3, Z scores from the initial screen of 4.4, 3.3 and 8.5 respectively)." (PMID 22082156, 2011).
tumor (1 paper, 2017). "The main functions of the top genes in OSPC2 network were associated to sensitization to chemotherapy (CXCR4, ANKRD1, CYR61, EDN1, ATP1B1, ARHGEF1, RTF1), and tumor suppression (FGFR3, BCL11B)." (PMID 28482906, 2017).
RTF1 also shares sentences with these, for which no sentence is quoted: amyotrophic lateral sclerosis (1 paper); arrhythmogenic right ventricular dysplasia 5 (1); autism (1); Charcot-Marie-Tooth disease (1); conduct disorder (1); epilepsy (1); Intellectual disability (1); neuropathy (1).